APOE (apolipoprotein E)
Diseases named in the same sentence as APOE in open-access papers (continued):
Sharing a sentence is not in itself a finding about the gene and the disease.
dementia (continued). "The National Alzheimer’s Coordinating Center (NACC) conducted a prospective cohort study that reported exposure to vitamin D was associated with significantly lower incidence of dementia in both APOE ε4 carriers and non-carriers, but the effect was greater in non-carriers." (PMID 37246226, 2023). "Moreover, among participants with BMI gain >10%, APOE ɛ4 carriers were associated with a higher risk of dementia compared with noncarriers (HR = 6.81, 95% CI 1.52–47.4)." (PMID 35921193, 2023). "First, we were not able to collect information on educational level or apolipoprotein E ε4 level, which may be associated with risk of dementia." (PMID 36656579, 2023). "However, mechanisms remain elusive and there could be other explanations for an interplay between diet and APOE ε4 status in relation to dementia." (PMID 34632537, 2022). "Compared to the reference group (glucosamine users and APOE ε4 non-carrier), the glucosamine non-users and APOE ε4 carrier group (HR = 2.80, 95% CI: 2.58–3.04) was strongly associated with an increased risk of dementia." (PMID 36514123, 2022). "When we investigated the combined effect of PPI use and APOE ε4, the results showed a significantly increased risk of dementia in ε4 homozygotes, regardless of whether they used PPI or not." (PMID 36045363, 2022). "APOE ε4 non-carriers with a higher adherence to the healthy dietary pattern had a reduced risk of dementia in model 1 (HR 0.79; 95% CI 0.65–0.95) and in the fully adjusted model 2 (HR 0.77; 95% CI 0.61–0.98), but no such associations were found among APOE ε4 carriers." (PMID 34632537, 2022). "Therefore, in the study population, APOE ε4 proved to be a risk factor for the existence of cognitive deficits, contributing to doubling the risk of having a score of CDR >1 (OR = 2.527; p = 0.031), often associated with dementia." (PMID 39081475, 2022). "In this large, community-based cohort, APOE ε4 homozygosity was independently associated with sleep disturbance after controlling for the extent of AD neuropathological change, age, gender and affective symptoms, in individuals both with and without dementia." (PMID 35354468, 2022). "In that context, it is intriguing whether or not the APOE genotype impacts the association between a physically active lifestyle and the development of dementia, particularly in AD." (PMID 36153580, 2022). "Taken together, a gap in our knowledge remains whether APOE is functionally related to cellular metabolism that influences tau phosphorylation or facilitates intercellular transfer of tau or both in AD and related dementias." (PMID 35440098, 2022). "Also, significant associations between LS7 scores and composite lifestyles with dementia were observed only among APOE ε4 allele non-carriers, yet not in the carriers." (PMID 35619174, 2022). "The study aimed to determine whether APOE genotype is associated with alpha rhythm characteristics of spontaneous EEG in adults without dementia during aging." (PMID 35979332, 2022). "To date, the linkage between PA, risk of dementia, and APOE ε4 status are not clear." (PMID 35418852, 2022). "A study reported that protective variants of APOE against risk of AD also slow cognitive decline in patients with dementia, regardless of cholesterol variations, while therapy with lipophilic statins might benefit carriers of specific genetic variants." (PMID 39081475, 2022). "Secondary analysis showed a dose-dependent risk of developing PDD associated with APOE-ε4: when compared to non-carriers, carriers of one ε4 allele were at 3.1 times higher risk of progressing to dementia, while those who carried two ε4 alleles were at 6.4 times higher risk." (PMID 35106798, 2022). "In contrast, by binding to the regulatory factor X1 (RFX1) mRNA, miR-124 could increase the expression of RFX1, resulting in the suppression of apolipoprotein E (APOE) and cellular amyloid beta (Aβ) in microglia, which could undermine the cognitive behavior of dementia." (PMID 35592472, 2022).
dementia (continued). "APOE ε4 carriers may have higher levels of glycation compared to non-carriers increasing their risk for dementia." (PMID 36083988, 2022). "Furthermore, when discussed in relation to genetic risk factors, the Rotterdam Study reported that a healthy lifestyle including diet reduced the risk of dementia in individuals with genotypes that did not carry apolipoprotein E (APOE) ε4 allele." (PMID 35276996, 2022). "Similar to our associations with cognitive performance, in a recent UK Biobank study higher processed meat intake associated with higher risk and higher unprocessed meat intake with lower risk of dementia and AD, without effect modification by the APOE phenotype." (PMID 35217900, 2022). "APOE-ε4 heterozygosity was similarly associated in individuals without dementia (β 1.21, p=0.048)." (PMID 35354468, 2022). "Another study found less robust prediction of dementia propensity scores in non-Hispanic Black participants in the USA compared with non-Hispanic White participants using a genetic risk score incorporating APOE and nine other SNPs." (PMID 36477264, 2022). "Compared to the APOE ε4 noncarrier, the risk of dementia among ε4 heterozygotes may be further amplified with regular PPI use." (PMID 36045363, 2022). "However, neither diet score was significantly associated with incident dementia in multivariable adjusted models, nor when restricting to participants of European ancestry and further adjusting for APOE ε4 status (model 3, data not shown)." (PMID 36615690, 2022). "Moreover, CREDOS data was also very useful in studying APOE prevalence in Korean dementia patients." (PMID 35197840, 2022). "Although we could not confirm the cause-effect relationship between dementia development and comorbidity occurrence, the interaction of ApoE polymorphism and these clinical illnesses certainly modifies the dementia risk." (PMID 36578446, 2022). "We replicate findings that APOE impact on dementia risk is not affected by global ancestry." (PMID 36477264, 2022). "However, as few studies have investigated the impact of the APOE phenotype on the associations between diet and cognitive decline and the findings are inconsistent, future studies are needed to elucidate the role of the APOE phenotype in the diet-dementia relationship." (PMID 35217900, 2022). "Our observation of a higher risk of dementia in noncarriers could be due to the substantially elevated baseline risk of dementia in APOE-ε4 carriers, which could attenuate the relative risk of dementia associated with multimorbidity within this group." (PMID 36125811, 2022). "Third, we could not include several major risk factors of dementia in the analyses such as the ε4 allele of the Apolipoprotein E (APOE), hearing loss, history of traumatic brain injury, and the level of education." (PMID 35710453, 2022). "However, the association between the 1e–5 AD‐PRS and incident dementia in the total sample (not stratified by APOE ɛ4 status) was slightly attenuated after removal of the SNPs (for all analyses: P = .06)." (PMID 33532541, 2021). "However, the association between GFR and dementia was not modified by age (≥ 70 or < 70 years old), baseline diabetes, hypertension, APOE-ε4, serum creatinine (≥ 0.85 or < 0.85 mg/dl), and BMI (≥ 24 or < 24 kg/m2) (Pinteraction > 0.05 for all)." (PMID 33430940, 2021). "In addition, a cohort study from eastern Finland showed that the APOE ε4 genotype did not modify associations of egg and cholesterol intakes with risk of incident dementia and AD over ∼22 y of follow-up." (PMID 33748832, 2021). "Yet another study from the UK Biobank (N = 196,383 average age: 64.1 years and median follow-up 8.2 years) found that favorable lifestyle profile was related to lower dementia risk regardless of the genetic dementia risk measured by a polygenetic risk score including APOE genotype." (PMID 34061824, 2021).
dementia (continued). "For smokers among APOE-ε4 allele carriers, the prevention strategies on dementia might be more effective by alleviating the negative effect of APOE ε4 allele and smoking via other composite measures rather than solely through smoking control." (PMID 34155245, 2021). "In the development of a potential screening approach, a decision tree was performed considering the neuropsychological tests (dementia, non-dementia), the previously validated diagnosis model (positive, negative), and the genotype ApoE (allele ε4 carrier, non-carrier)." (PMID 34829533, 2021). "Our findings suggest that consumption of processed meat may increase risk of incident dementia, and unprocessed red meat intake may be associated with lower risks, independent of APOE ε4 carriage." (PMID 33748832, 2021). "The patient was a heterozygote carrier for apolipoprotein-E ε4 that increases the risk of sporadic Cerebral Amyloid Angiopathy (CAA), which is characterized by beta-amyloid accumulation and fibrinoid necrosis in cerebral vasculature leading to micro/macrohemorrhages and dementia." (PMID 34386418, 2021). "In other words, for a fixed chronological age, APOE status and gender, increase of biological age was found to be associated with elevated risk of all-cause mortality as well as major ARDs such as coronary heart disease, diabetes, cancer, stroke, COPD and dementia." (PMID 34354164, 2021). "However, APOE ε4 carriers but not noncarriers had reduced risks of incident all-cause dementia and incident AD per 50 g/d increment of unprocessed red meat." (PMID 33748832, 2021). "For men, there was significant additive interaction (RERI 3.81, 95% CI 0.67–6.96; AP 0.40, 95% CI 0.14–0.66; S 1.81, 95% CI 1.09–3.01) between one APOE-ε4 allele carriers and former smoking on dementia risk while non-significant multiplicative interaction was identified (HR 1.49; 95% CI 0.92–2.41)." (PMID 34155245, 2021). "We believe that this work is timely in the emerging landscape of preventive trials for dementia in DS given that consideration of APOE genotype might be important for drugs that are designed to lower amyloid burden and/or trials that use MRI as a surrogate marker of improved outcomes." (PMID 34228042, 2021). "APOE genotype but not polygenic risk modified the effect of smoking on dementia risk." (PMID 34155245, 2021). "Finally, several confounding factors, such as the ApoE genotype, significantly affecting dementia risk, were not explored in this study." (PMID 34674153, 2021). "Previous stratified analyses by APOE ε4 status showed that unfavourable lifestyle factors (e.g., less healthy dietary pattern, less physical activity, smoking, and social isolation) were associated with higher risk of dementia in APOE ε4 noncarriers but not in carriers." (PMID 33748832, 2021). "Similarly, in a separate cohort, women had higher tau and p-tau concentrations in early stages of mild cognitive impairment (MCI) and subjective cognitive decline, while among non APOE e4 carriers, women had higher concentrations at the later stages of AD, dementia, and MCI." (PMID 34899299, 2021). "The relation between ApoE ε4 and CVD might also determine the risk and prevalence of dementia." (PMID 35011591, 2021). "Interestingly, the presence of apolipoprotein E (APOE; ApoE) ε4 allele or vascular risk factors did not change the association between either of these vascular pathologies and dementia outcome." (PMID 34331941, 2021). "PRS could predict the conversion of MCI to dementia with a stronger association in APOE ε4 non-carriers than APOE ε4 carriers." (PMID 34465370, 2021). "The carriage of the APOE ε4 allele may influence functional connectivity in older adults without dementia." (PMID 34267235, 2021). "In addition, stratified analyses for APOE ε4 status revealed that higher concentrations of EPA were associated with a decreased incidence of all-cause dementia and AD dementia among APOE ε4 non-carriers but not among APOE ε4 carriers." (PMID 33573174, 2021).
dementia (continued). "Specifically, two APOE-ε4 alleles carriers were at greatest risk of dementia followed by one-ε4 allele carriers compared with non-carriers, with an adjusted hazard ratio (HR) of 7.63 (95% confidence interval [CI] 6.46–9.01) and 2.47 (95% CI 2.22–2.76), respectively." (PMID 34155245, 2021). "Increasing education, in particular, may be relevant to this high-risk group as low education comes with a higher dementia risk in APOE e4 allele carriers than in non-carriers." (PMID 34366944, 2021). "MCI patients affected by agitation/aggression or appetite/eating symptoms are not so frequent, but when they additionally present an APOE ε4 carrier status become the patients with the poorest prognosis, that is, have the highest risk of progression to dementia." (PMID 33208795, 2020). "Findings from the exploratory FINGER PET sub-study suggest that a model combining demographic data, vascular risk factors, cognitive performance, APOE genotype, and brain MRI measures can detect Aβ positivity in older at-risk individuals without dementia or substantial cognitive impairment." (PMID 32848707, 2020). "Thus far, investigations of total apoE levels in relation to dementia risk have not accounted for the distribution of apoE among a heterogeneous mix of lipoproteins." (PMID 32648923, 2020). "We could not consider the role of APOE e4, the major susceptibility allele for dementia, due to lack of data." (PMID 32528407, 2020). "Initially, the authors showed that APOE*E4/*E4 homozygotes were more likely to be SARS-CoV-2 positive when compared to APOE*E3/*E3 homozygotes, regardless of presence of APOE*E4-associated diseases (dementia, hypertension, coronary artery disease, type 2 diabetes)." (PMID 32803253, 2020). "In this regard, age, sex, and APOE ε4 allele combined with plasma NFL and t-Tau may be used to establish a risk stratification score integrating different information on the development of dementia." (PMID 33183357, 2020). "APOE ɛ4 and long work duration may amplify the impact of passive jobs on dementia." (PMID 32081835, 2020). "Moreover, non-modifiable factors, such as age and APOE ε4, significantly increase the risk of dementia and should be taken into account." (PMID 32767997, 2020). "Furthermore, we determined whether APOE e4 genotype might affect clinical progression measured by a clinical dementia rating sum of boxes (CDR-SB) score in AD, L-aMCI, E-aMCI, and SMI." (PMID 32770103, 2020). "In addition, we detected a multiplicative interaction between passive jobs and APOE ɛ4 with respect to estimating dementia risk among the younger-old (p<0.05), but not among the older-old." (PMID 32081835, 2020). "The APOE ε4 allele is not a risk factor for PD, but it is a risk factor for dementia." (PMID 33013627, 2020). "The statistical interactions were observed between rosuvastatin and APOE ε4 allele on the changes in MMSE (Padjusted = 0.018), MoCA (Padjusted = 0.020), DRS (Padjusted = 0.031), CDR (Padjusted = 0.027), and IQCODE (Padjusted = 0.022) and in the dementia (Padjusted = 0.022)." (PMID 32581766, 2020). "Increased levels of oxidative stress and the E4 allele of apolipoprotein E (ApoE) have been found in the CNS of an HIV-infected population or in individuals with a history of intravenous drug abuse, and were considered as the risk factors contributing to the development of dementia." (PMID 32215172, 2020). "In addition, future genome-wide analysis of gene–gene interactions may indicate that the role of APOE*ε4 in the aetiology of dementia, depression and other disease is moderated by other genes." (PMID 32381152, 2020). "Therefore, we propose that the link between genetic factors operable in TGA and its relationship to dementia family history may be through an APOE e4-like mechanism." (PMID 32143587, 2020).
dementia (continued). "Although it remains controversial whether and how peripheral APOE may contribute to AD pathogenesis, evidence suggests that low plasma APOE levels are associated with increased AD and dementia risk, independent of APOE genotype." (PMID 33148290, 2020). "We hypothesized that higher apoE levels in HDL are inversely associated with risk of dementia but only in the absence of apoC3." (PMID 32648923, 2020). "Patients with dementia are at an increased risk for sleep disorders, including OSA relative to age-matched controls, with prevalence estimates of OSA as high as 50–70%; this risk is elevated among individuals who are carriers of the APOE-ε4 (apolipoprotein-E) allele." (PMID 31900098, 2020). "The hazard ratios (HRs) for apoE level in HDL that contained or lacked apoC3 with dementia risk were statistically significantly different (HR per 1-SD higher apoE in HDL that contained apoC3: 1.07 [95% CI, 0.95-1.19] vs 0.86 [95% CI, 0.76-0.99]; P for heterogeneity = .03)." (PMID 32648923, 2020). "Among the genes associated with both CMBs and dementia, the NOTCH3 and APOE genes were both found to be involved in AP-2 transcription regulation, suggesting that vitamins, growth factors, and vesicle-mediated transport may contribute to CMBs-associated dementia." (PMID 33352859, 2020). "First, we could not adjust for some well-known associated factors for dementia such as apolipoprotein E genotype, diet, reproductive experiences such as breast feeding, and gynecological surgery that could be associated with parity." (PMID 32753059, 2020). "Multivariable logistic regression analysis revealed that lactic acid concentration was associated with the presence of dementia, independent of age, sex, education years, ApoE ε4, risk factors, and brain MRI and/or SPECT abnormalities (OR = 0.1, 95% CI 0.01–0.5, P = 0.001)." (PMID 32424166, 2020). "Second, the apolipoprotein E (APOE) gene was included, the best-known genetic risk factor for dementia; based on previous work, we hypothesised that the ε4 allele of this gene would be negatively associated with the ACE-III score but not with childhood cognition." (PMID 31023749, 2019). "Analogous to this study, others have found that in European Americans, APOE ε4+ individuals did not receive the same benefits as APOE ε4− individuals from higher levels of aerobic fitness or following an exercise intervention, with fitness only reducing the risk for dementia in non-carriers." (PMID 31749691, 2019). "Alongside these studies, it will also be crucial to investigate the effect of the host on tau oligomer formation; for factors like the genetic makeup such as APOE and TREM2 alleles also affect tau oligomers and thus contribute to determining the risk for neurodegeneration and late-life dementia." (PMID 31608324, 2019). "In line with the hypothesis that downregulation of IGF-I signaling is associated with increased dementia risk, ApoE-ε4 homozygotes without prevalent dementia displayed lower levels of IGF-I receptor stimulating activity than heterozygotes and non-carriers." (PMID 30809143, 2019). "However, evidence supporting the association of APOE ε4 allele with MCI or cognitive impairment no dementia remains mixed." (PMID 31214016, 2019). "Finally, another study found that both dementia and diabetes but not apolipoprotein E genotype or amyloid pathology were associated with blood-brain barrier permeability." (PMID 31194855, 2019). "Since we did not have genetic polymorphisms of ApoE for additional analyses, whether this might have explained the lack of a protective effect of rosiglitazone on dementia in our patients with type 2 diabetes mellitus remains to be answered." (PMID 31085804, 2019). "However, no relation between IGF-I receptor stimulating activity and dementia risk was observed in non-carriers of the ApoE-ε4 allele." (PMID 30809143, 2019).